IL6 (interleukin 6)
Diseases named in the same sentence as IL6 in open-access papers (continued):
Sharing a sentence is not in itself a finding about the gene and the disease.
malaria (continued). "Because IL-1β and IL-6 are primarily produced by monocytes/macrophages, we isolated monocytes/macrophages from 9 additional children who had PBMCs available at their healthy baseline before the malaria season and 14 days after their first febrile malaria episode of the ensuing malaria season." (PMID 24743880, 2014). "Elevated levels of circulating tumor necrosis factor (TNF), interleukin-6 (IL-6), IL-12, IL-1β, and IL-10 have been reported to correlate with malaria disease severity and with fatal outcomes; the behaviour of these cytokines in asymptomatic parasitaemia remains unknown." (PMID 24642188, 2014). "An in vitro study found that BAT1 appeared to decrease the expression of TNF and IL-6; thus the G allele of DDX39B-22C > G, which enhances the expression of BAT1, may be protective against complicated malaria by decreasing the expression of proinflammatory cytokines." (PMID 25038626, 2014). "Inflammatory factors, other than hepcidin, may inhibit erythroblast iron incorporation as this was not correlated with hepcidin, malaria, or IL-6, but was significantly associated with raised CRP values." (PMID 24339866, 2013). "While a specific role of DC IL-6 production during malaria is unknown, IL-6 is considered an important regulator of the transition from the innate to acquired immune responses and it may also influence DC maturation via the inhibition of nuclear factor kappa B (NFκB)." (PMID 19077314, 2008). "Plasma adipsin showed strong positive correlations with C5a (ρ = 0.695), IL‐6 (ρ = 0.687), and TNF‐α (ρ = 0.645), and moderate correlations with malaria parasite density (ρ = 0.553), IL‐8 (ρ = 0.475) and C3a (ρ = 0.437) (p < 0.001 for all)." (PMID 41536443, 2026). "On admission, the concentrations of IL-1β (p = 0.0026), IL-2 (p < 0.0001), IL-6 (p = 0.0009), TNF-α (p > 0.0001), and IFN-γ (p > 0.0001) were significantly upregulated in patients with malaria and typhoid comorbidity, comparing to healthy controls." (PMID 40014608, 2025). "It is known that malaria disease induces multiple inflammatory signs besides several cytokines like TNF-α and IL-6 playing a significant role in the inflammatory process." (PMID 40917784, 2025). "While cytokines such as IL-6 and tumor necrosis factor-α (TNF-α) have been extensively studied in malaria pathogenesis, the role of IL-2 remains poorly understood and inconsistently reported across studies." (PMID 41194029, 2025). "In humans, malaria during pregnancy results in elevated levels of numerous cytokines, including IFN-γ, TNF-α, IL-4, IL-6, IL-10, and CXCL9 in peripheral circulation, with some of these cytokines linked to increased risk of pregnancy loss." (PMID 40470930, 2025). "Strong correlations between IL-6 and APOA1 levels in children with malaria suggest that APOA1 increases as the inflammatory response intensifies, potentially serving as a protective mechanism." (PMID 40061813, 2025). "The findings highlight the potential of IL-6, TNF-α, and APOA1 as biomarkers and therapeutic targets in malaria." (PMID 40061813, 2025). "The pathophysiological mechanism of pain and other symptoms can involve the release of inflammatory cytokines, especially TNF-α, IL-1, IL-6, IFN-γ, IL-8, IL-10, and IL-13, during the inflammatory response induced by malaria." (PMID 38774541, 2024). "The prognostic capacity of biomarkers, plasma IL-6, IL-8, TNF, sRAGE, SP-D and KL-6 on admission for a prediction of clinical pulmonary oedema in severe malaria is poor." (PMID 39448997, 2024). "Since it has been shown that blood levels of cytokines are altered during malaria, levels of the serum cytokines TNF-α, IFN-γ, IL-10, and IL-6 of uninfected and PbA-infected mice at day 7 post-infection were determined using CBA analysis." (PMID 38787228, 2024). "Malaria presents with enhanced release of TNF‐α, IFN‐ɣ, IL‐1β, IL‐6, GM‐CSF, and IL‐10, but downregulates IL‐3 and TGF‐β in Ghanaian children." (PMID 39240033, 2024).
malaria (continued). "Malaria‐infected children had relatively higher TNF‐α (p < .001), IFN‐ɣ (p < .001), IL‐1β (p < .001), IL‐6 (p < .001), GM‐CSF (p < .001), and IL‐10 (p < .001) levels than uninfected participants." (PMID 39240033, 2024). "In the current study, participants with malaria had higher TNF‐α/IL‐10, TNF‐α/TGF‐β, IFN‐ɣ/TGF‐β, and IL‐1β/TGF‐β, but lower IFN‐ɣ/IL‐10, IL‐1β/IL‐10, and IL‐6/TGF‐β ratios than those in the control group." (PMID 39240033, 2024). "IL-6, IL-8, TNF, sRAGE, SP-D, CC16 and KL-6 cannot be used in predicting clinical pulmonary oedema in severe malaria patients." (PMID 39448997, 2024). "Severe malarial anemic children had elevated TNF‐α (p < .001), IFN‐ɣ (p < .001), IL‐1β (p < .001), IL‐6 (p < .001), GM‐CSF (p < .001), and IL‐10 (p < .001), but lower IL‐3 (p < .001) and TGF‐β (p < .001) than those with uncomplicated malaria." (PMID 39240033, 2024). "Severe malaria patients have been found to produce high levels of systemic proinflammatory cytokines such as IFN-γ, IL-1β, IL-6, and TNF-α." (PMID 38787228, 2024). "Participants with malaria had higher TNF‐α/IL‐10, TNF‐α/TGF‐β, IFN‐ɣ/TGF‐β, IL‐1β/TGF‐β and, but lower IFN‐ɣ/IL‐10, IL‐1β/IL‐10, and IL‐6/TGF‐β ratios than those in the control group." (PMID 39240033, 2024). "The results herein provide evidence for the association of TLR4 and related genes, ICAM1, IFNGR1, IL13, and IL6, as well as ABO, with the incidence of clinical malaria." (PMID 37287037, 2023). "In summary, our work supports the hypothesis that increased IL-6 is not causal for severe malaria." (PMID 36801374, 2023). "The choice of cytokines and chemokines measured was based on their reported implication in severe malaria (i.e. IFNγ, TNF-α, IL6, IL-1β, RANTES, MIP-1, MCP-1, IP10)." (PMID 37350957, 2023). "For instance, increased levels of IL-12, IL-6, IL-10, IL-1β and IFN-γ have been identified during severe malaria whereas low levels of 1L-12p70, IL-10, IFN-α, and IFN-γ have been associated with SM in children." (PMID 37525227, 2023). "Distinct cytokine profiles in malaria and intestinal parasite coinfections were TNF, IL-2, IL-4, IL-6, and IL-10." (PMID 36716305, 2023). "Increased TNF, IFN-γ, IL-6, IL-10, IL-17, CCL2, and CCL3 levels and decreased IL-7 levels were observed in malaria monoinfection compared to dengue virus monoinfection." (PMID 36716305, 2023). "Most of the cytokines that were investigated in malaria and other parasite coinfections were TNF, IFN-γ, IL-2, IL-4, IL-6, and IL-10." (PMID 36716305, 2023). "Activation of monocytes by IFN-γ results in classical activation of macrophages, leading to the release of pro-inflammatory cytokines such as IL-6 and TNF-α, and increased concentration of IFN-γ has been observed during both babesiosis and malaria." (PMID 36839438, 2023). "Distinct cytokine profiles in malaria and HBV coinfections were TNF, IFN-γ, IL-4, IL-6, IL-10, IL-12, and CCL2." (PMID 36716305, 2023). "Distinct cytokine profiles in malaria and human African trypanosomiasis coinfections were TNF, IFN-γ, IL-6, and IL-10." (PMID 36716305, 2023). "For intestinal parasite infections, increased TNF, IL-1, IL-6, IL-10, CCL2 and decreased IL-4, IL-17, TGF-β were observed in malaria coinfections compared to intestinal parasite monoinfection." (PMID 36716305, 2023). "For malaria and virus coinfections, increased TNF, IFN-γ, IL-6, and CCL4 levels and decreased IL-4, IL-7, IL-12, TGF-β, and CCL3 levels were observed in malaria coinfections compared to dengue monoinfection." (PMID 36716305, 2023). "Malaria and dengue coinfections showed a significant increase in proinflammatory cytokines such as IFN-γ, IL-1, IL-6, and IL-12; Th2 cytokines such as IL-4; anti-inflammatory cytokines such as IL-10 and IL-13; and Th17 cytokines such as IL-17." (PMID 36716305, 2023). "IL-6, IL-13, TNF-α, and IFN-γ were significantly higher in severe malaria, while IL-7, IL-10, IL-17, and IL-27 showed the opposite trend." (PMID 36293524, 2022).
malaria (continued). "As expected, inflammatory cytokines such as IL-6, IFN-γ, and TNF-α were much higher in severe than in mild malaria patients." (PMID 36293524, 2022). "Pyrogenic cytokines Interlukin-1 IL1, IL6, and Tumor Necrosis Factor (TNF) are produced in response to malaria parasites." (PMID 35720297, 2022). "Increased levels of proinflammatory cytokines such as interleukin-1 beta (IL-1β), IL-6, IL-8, IL-10, IL-12, IL-13, IL-31, IL-33, and tumor necrosis factor alpha (TNF-α) have been reported to be related to clinical malaria or severe malaria." (PMID 35396564, 2022). "It is worth of noting that despite the decrease in IL-6, this coinfected group showed higher values of TNF-α than malaria." (PMID 35749690, 2022). "The subgroup IL-15, IL-17 and IL-4 was negatively correlated to the cohort containing IL-6, IL-1Ra MIP-1β, IL-7 and IP-10, which, interestingly, has been shown to be a marker for different infections including malaria and dengue fever." (PMID 34299123, 2021). "For cytokines IL-6, IL-1RA, IL-10 and IL-11 and chemokines CXCL1, CXCL8, CXCL10, CCL3 and CCL2, significantly higher concentrations were found in plasma samples of malaria patients compared to healthy controls." (PMID 34359826, 2021). "The correlation was strongest for IL 10 (r=0.63 p>.0001 and r=0.53, p<.0001 respectively), followed by IL6 (r=0.59, p<.0001) in asymptomatic malaria, and TNF-α in clinical malaria (r=0.48, p<0.001)." (PMID 34177883, 2021). "In the Mali cohort we found that monocytes of adults produced lower levels of the inflammatory cytokines IL-1β, IL-6 and TNF in response to Pf-iRBC stimulation compared to monocytes of infants and children, or malaria-naïve U.S. adults." (PMID 33822828, 2021). "Significantly lower cytokine responses (IL-1β, IL-6, IL-10, TNF-α and IFN-γ) to LPS and Staphylococcus aureus were observed among participants with asymptomatic malaria compared to controls." (PMID 34177883, 2021). "Production of pro-inflammatory cytokines and chemokines such as IL-1β, IL-6, IL-8, IL-12, IFN-γ, and TNF induce fever and other signs and symptoms in previously unexposed individuals resulting in severe and fatal malaria." (PMID 33746974, 2021). "The markers forming the first cluster tended to increase the MDP values in the group of symptomatic malaria, with remarkable high values of TNF-α, IL-6, CXCL9, AST, CRP, IL-8 and ALT." (PMID 34727121, 2021). "CXCL9 and IL-4 were the top markers when we analyzed asymptomatic malaria vs. controls, whereas IL-6 and CXCL10 were highlighted when symptomatic vs. asymptomatic malaria patients were compared." (PMID 34727121, 2021). "We found that monocytes of Malian adults produced lower levels of the inflammatory cytokines IL-1β, IL-6 and TNF in response to Pf-iRBC stimulation compared to monocytes of Malian infants and children or malaria-naïve U.S. adults." (PMID 33822828, 2021). "Furthermore, whereas transfusing a 500 mL malaria-infected donor whole blood stored for 21 days may result in infusing 190 ng of IL-6, transfusing an equivalent volume of nonmalaria-infected blood will result in infusing only 11.4 ng of IL-6." (PMID 33195706, 2020). "Levels of circulating pro- (IL-6, TNF-α and IFN- Υ) and anti-inflammatory cytokines (IL-10) were highest in clinical malaria." (PMID 33253198, 2020). "In this study, it was confirmed that the baseline levels of inflammatory cytokines IL-6, IL-10, IL-12, and TNF-α in malaria-infected donor blood (parasitaemia, 515-1877 parasites/μL of blood) were significantly higher compared to noninfected controls." (PMID 33195706, 2020). "It is interesting to note that IL-6 was found to be elevated in leptospirosis, DHF, chikungunya, hanta virus, malaria and Ebola infections." (PMID 32264832, 2020). "In some cases, a surge in inflammation due to malaria infection leads to severe or moderate malaria, specifically due to higher levels of circulatory pro‐inflammatory cytokines, such as TNF and IL‐6, but IL-10 regulates the outcome." (PMID 32033605, 2020).
malaria (continued). "Among the severe malaria cases, TGF-β content was inversely correlated with the pro-inflammatory cytokines IFN-γ and IL-6, but perplexingly also the anti–inflammatory cytokine IL-10." (PMID 32043415, 2020). "In contrast, a separate study showed that monocytes from children with severe malaria had an impaired ability to produce inflammatory cytokines (TNF and IL‐6) to in vitro TLR agonists such as LPS." (PMID 32566226, 2020). "We show that individuals with microscopic asymptomatic malaria had significantly increased levels of TNF-α and IL-6 compared to uninfected controls." (PMID 33281757, 2020). "There was a positive correlation between IL-6 and IFN-ɣ in HIV seropositive pregnant women with malaria coinfection (r = 0.479, p=0.006)." (PMID 33193759, 2020). "Studies in malaria-endemic countries have found that it is crucial to have a balance between a host pro-inflammatory, Th1 response (e.g., TNF, IL-6, IL-12, and interferon-gamma) and anti-inflammatory, Th2 response (IL-4, IL-10, and others)." (PMID 33357220, 2020). "Malaria and HAT co-infection modified synergistically the pro-inflammatory (IFN-γ, TNF-α) and anti-inflammatory (IL-6, and IL-10) cytokine response than P. falciparum mono-infections." (PMID 31687034, 2019). "The assay was carried out for five plasma cytokines (IFN-γ, TNF-α, IL-6, IL-10, and TGF-β) in HAT and/or malaria cases and healthy controls." (PMID 31687034, 2019). "Peripheral blood mononuclear cell (PBMC)-derived primary macrophages express increased levels of IL-6, IL-10, IL-1β, and TNF in malaria cases." (PMID 31662766, 2019). "Malaria and/or HAT cases presented significant higher plasma cytokine levels of IFN-γ, TNF-α, IL-6, IL-10 and TGF-β than healthy controls (P < 0.05)." (PMID 31687034, 2019). "In the current study, IL-6 and IL-10 levels were significantly elevated in HAT similar to co-infected cases over malaria mono-infection." (PMID 31687034, 2019). "Since both IL-6 and IL-10 have been found to be up-regulated in ATBF and MSF as well as IL-10 in malaria, these results suggest common effects of R. felis and P. falciparum." (PMID 29736763, 2018). "When whole blood was stimulated in vitro with LPS, monocytes from children with severe malaria produced less proinflammatory cytokines TNF-α and IL-6 than cells from healthy controls." (PMID 30581439, 2018). "For example, an elevated expression of IL-1, IL-6, IL-12, IFN-γ and TNF was found in severe malaria and in hyperparasitemia, a primary clinical feature of severe disease." (PMID 30022038, 2018). "Using our well-defined prospective cohort, we preliminarily screened six candidate Th1 cytokines (IL-1, IL-6, IL-12, IFN-γ, TNF and TNF-β), and identified IL-12 as a promising molecule for malaria protection." (PMID 30022038, 2018). "We observed decreased IL-6 and TNF-α production by monocytes in children with different forms of malaria." (PMID 28122790, 2017). "Severe malaria patients display increase levels of pro-inflammatory cytokines, TNF, IL-6 and IFN-γ while acute malaria individuals show high levels of the anti-inflammatory cytokines IL10." (PMID 28288644, 2017). "There were significant positive correlations between parasite density in children with malaria and levels of key pro-inflammatory cytokines, including TNF-α, IFN-γ and IL-6." (PMID 28399920, 2017). "During acute malaria, percentages of TNF‐α‐ and IL‐6‐producing monocytes in all clinical groups were significantly lower than in controls, with children with CM having the lowest percentage." (PMID 27027867, 2016). "Plasma levels of inflammatory cytokines (IFNα, IFNγ, TNF, IL-6) and chemokines (CCL2, CCL3, CCL4, CXCL10) were significantly higher during severe malaria compared to convalescence." (PMID 27792766, 2016). "IL-6 and TNF-α belong to the innate cytokines, they play important roles in the pathogenesis of malaria." (PMID 25889652, 2015).
malaria (continued). "In order to demonstrate the role of cytokines in the modulation of HAT progression, we assayed six cytokines (IFN-γ, IL1-β, TNF-α, IL-6, TGF-β and IL-10) in plasma of both cases (N = 49, after excluding 6 malaria co-infected patients) and controls (N = 41)." (PMID 26090964, 2015). "Network analyses of plasma cytokines/chemokines revealed that malaria and dengue co-infection exhibits a distinct immune profile with critical roles for TNF, IL-6 and IFN-γ." (PMID 26271921, 2015). "Network analyses revealed that cases of malaria and dengue co-infection exhibit a unique immune profile with a special role for TNF, IL-6, IFN-γ, and IL-7." (PMID 26271921, 2015). "Further, parasitaemia levels displayed positive significant interactions with IL-6, CCL4 and IL-10 in the group of patients co-infected with malaria and dengue." (PMID 26271921, 2015). "Amongst the clinical groups evaluated, the group of individuals with malaria and dengue co-infection exhibited the highest median concentrations of IFN-γ, IL-6, CCL4." (PMID 26271921, 2015). "Circulating levels of interferon (IFN)-γ, interleukin (IL)-2, IL-4, IL-6, IL-10, IL-12p70, IL-13, IL-17A and tumor necrosis factor (TNF) were assessed in sera of patients infected with active VL and/or malaria and healthy individuals from Gedarif State, Sudan." (PMID 24886212, 2014). "In both malaria and coinfected groups the median levels of TNF-α, IL-2, IL-10, IL1-β, MCP-1, and IL-6 were observed to be mostly significantly increased compared with those intestinal parasites and uninfected groups (P < 0.001 for all comparisons)." (PMID 25309052, 2014). "The importance of IL-6 and CXCL-8 has been shown in malaria, which are produced mostly by monocytes." (PMID 24741587, 2014). "Clinical malaria cases exhibited an immunological profile qualitatively similar to that of the VL patients, with increased concentrations of TNF, IL-6 and IL-10 (P <0.0001) and, to a less extent, IFN-γ and IL-17A (P <0.01), IL-4 and IL-12p70 (P <0.05)." (PMID 24886212, 2014). "Previous studies on the impact of cytokines on clinical outcome in malaria have identified TNF, IFN-γ, IL-1β, IL-6, IL-10, IL-12, transforming growth factor β and IP-10 as important mediators, but data on IL-8in this setting are more limited." (PMID 25503583, 2014). "In contrast, gene networks centred on TGFB1/IL6, IL-17, or IFN-αβ were more dramatically altered during the malaria disease cycle." (PMID 24188121, 2013). "After evaluating the cytokine profile (IL-2, IL-4, IL-6, IL-10, TNF-α, IFN-γ and IL-17) in the patients’ sera, levels of IL-6, IL-10 and IFN-γ were elevated in malaria patients compared to HV." (PMID 23723981, 2013). "Plasma endotoxin levels in severe malaria negatively correlated with IL6, IL10 and TGFβ (Spearman rho: TNFα: r=−0.122, p=0.121; IL6: r=−0.330, p<0.0001; IL10: r=−0.461, p<0.0001; TGFβ: r=−0.173, p<0.027)." (PMID 23497104, 2013). "UA levels also correlated with IL-6, IL-10, sTNFRII, MCP-1, IL-8, TNFα and IP-10 levels, all of which were elevated in children with severe malaria." (PMID 23071567, 2012). "Others have demonstrated the up-regulation of hepcidin in human and murine malaria, BMP- and IL-6-dependent in the latter, and a TLR2-dependent, IL-6-independent increase in Borrelia infection of mice." (PMID 22675442, 2012). "On the other hand, upon stimulation with LPS or Pam, high levels of IL-1β, IL-6, and TNF-α were produced by monocytes from malaria patients." (PMID 22745844, 2012). "Malaria-naïve adults experimentally infected with Pf had increased expression of TNF-α, IL-1β and IL-6 in response to a TLR4 ligand (LPS) and IL-6 and IL-10 in response to TLR2 + TLR1 ligand (Pam3Cys) on day 8 of the infection." (PMID 19691558, 2009). "In the biomarker subset, IL-6 was significantly higher in malaria-positive participants than malaria-negative participants (median 141.28 vs 106.58 pg/mL; p = 0.027), whereas HO-1 showed a non-significant upward shift (230.98 vs 193.73 ng/mL; p = 0.131)." (PMID 42220499, 2026).